RICTOR (RPTOR independent companion of MTOR complex 2)
Diseases named in the same sentence as RICTOR in open-access papers (continued):
Sharing a sentence is not in itself a finding about the gene and the disease.
cancer (continued). "In the present study we found that inhibition of the mTORC2 component RICTOR impairs activation of signaling pathways (AKT, SGK1), reduces expression of hypoxia-induced HIF-1α and diminishes secretion of critical cancer-promoting factors involved in stromal recruitment such as VEGF-A and IL-8." (PMID 28445935, 2017). "However, they shared with carcinomas a similar prevalence of copy gains in several genes, including the chromosome 5p genes TERT, SDHA, and RICTOR, but also SRC and MYCL." (PMID 27873319, 2017). "The genes of mammalian target of rapamycin (mTOR), RICTOR, and RAPTOR survival pathways, which are often overexpressed in majority of the cancers, were significantly downregulated within few hours of the treatment of SKOV3 cells with C1q and globular head modules." (PMID 28066412, 2016). "Mechanistically, we provide information about Lpd interacting with RICTOR as an important determinant downstream of EGFR signaling and thus demonstrate an additional facet of how a cytoskeletal protein takes part in the concerted actions evolving the hallmarks of cancer." (PMID 34771501, 2021). "Additionally, we did not observe significant changes in RICTOR methylation levels in other cancers." (PMID 37372460, 2023). "Although data shown here are based on genomic analysis of immortalized cell lines and therefore may not reflect clinical TNBC populations, RICTOR amplification has been shown to co-occur with PI3K pathway alterations in TNBC and other cancers at a relatively high frequency." (PMID 40019775, 2025).
tumor (68 papers, 2012 to 2026). "This is especially relevant in light of recent evidence that connect tumor immunogenicity with metabolic alterations reminiscent of those we observed in RICTOR-deficient cells." (PMID 38755661, 2024). "As a key effector molecule of PI3K/AKT/mTOR, RICTOR plays an important role in tumorigenesis and invasion and causes tumor resistance to RTK-TKIs by AKT-dependent and -independent pathways, which seriously limits patients’ benefits from targeted drugs." (PMID 32041519, 2020). "In short, RICTOR overexpression is associated with tumor malignancy and prognosis, which means RICTOR is a potential drug target." (PMID 32041519, 2020). "Whereas overexpression of RICTOR reduced susceptibility of HNSCC tumor cells to PI3K inhibition, genetic ablation of RICTOR using CRISPR/Cas9 sensitized cells to PI3K inhibition, as well as to EGFR inhibition and cisplatin treatment." (PMID 31393061, 2019). "Further, we investigated the survival compensatory pathways associated with RICTOR blockade, and we took a dual pathway inhibition approach to blunt rescue mechanism(s) to produce significant anti-tumor effects in vitro and in vivo." (PMID 30338041, 2018). "In this model, it has been observed that RICTOR and mSIN1 loss of function prevented tumor formation." (PMID 30662577, 2018). "Moreover, RICTOR expression has been found to be higher compared to normal tissues, inversely correlated with the Nottingham Prognostic Index and tumor grade, and associated with longer survival." (PMID 41300329, 2025). "Additionally, we employed the GEPIA2 database to investigate the relationship between RICTOR expression and tumor pathological stages, and observed a significant association in SKCM, OV, and TGCT." (PMID 37372460, 2023). "Furthermore, overexpression of RICTOR is associated with lymph node metastasis, tumor progression, and poor prognosis." (PMID 37046703, 2023). "Additionally, RICTOR deficiency results in a substantial decrease in pAktSer473 level and significantly reduces the proliferation of colorectal cancer cells and tumor growth." (PMID 35250965, 2021). "Furthermore, the amplification of RICTOR is also associated with tumor size, depth of invasion and tumor thrombosis, whereas p-Akt (Ser473) is associated with distant metastasis." (PMID 32041519, 2020). "More importantly, the increase in glucose and acetate could induce the acetylation of RICTOR via acetyl-CoA and maintain mTORC2 signaling through feedforward activation, causing tumor cells to counteract the TKI-mediated inhibition of upstream signals via AKT-independent pathways." (PMID 32041519, 2020). "RICTOR, a core component of the oncogenic mTOR2 complex, was altered in 21% of tumours, as was the tumour suppressor gene KMT2D." (PMID 41015991, 2025). "RICTOR, as an essential subunit of mTORC2, plays a tumor-suppressing role during the early adaptation phase of BRAFV600E melanoma cells to targeted therapy." (PMID 40775221, 2025). "The tumor-promoting role of the RICTOR protein and the probiotic nature of Bacteroidetes correlate with the observations of this study." (PMID 39907412, 2025). "As luminal tumor tissues show high RICTOR expression, we determined the effect of RICTOR silencing in MCF-7 and BT-474 cells." (PMID 40934285, 2025). "Prevalence, prognostic, and therapeutic implications of Rictor expression and/or RICTOR amplification in various tumor types." (PMID 38515456, 2024). "We aimed to assess in this context the role of mTORC2, a signaling complex defined by the presence of the essential RICTOR subunit, regarded as an oncogenic driver in several tumor types, including MM." (PMID 38755661, 2024). "It has also been shown in glioblastoma cells that RICTOR knockdown and subsequent inactivation of mTORC2 significantly decrease tumor cell migration by affecting the actin cytoskeleton and microtubule organization." (PMID 38339294, 2024).
tumor (continued). "AKT hyperactivation is another consequence of RICTOR upregulation, progressing tumor cells and decreasing overall survival." (PMID 37046703, 2023). "Employing kinase inhibitors or using RICTOR knockdown are other therapeutic approaches in mTORC2-targeted cancer therapy, leading to suppression of tumor cell growth, migration, and metastasis." (PMID 37046703, 2023). "Low tumour purity was associated with high expression of MYH11, RICTOR and CAV1, which are markers for mesenchymal lineage or EMT." (PMID 35083216, 2021). "To further address the tumor-promoting function of RICTOR and WDR59 in the mammary gland, we used a CRISPR activation (CRISPRa) approach 43,44." (PMID 34031411, 2021). "Together, these results clearly define a direct tumor-promoting function for RICTOR in the mammary gland." (PMID 34031411, 2021). "Direct targeting of RICTOR, the crucial component of mTORC2, led to impairment of tumor growth in vitro for CCA." (PMID 35096817, 2021). "In this review, we summarize the 1) the biology of RICTOR in tumor including the relationship between RICTOR and RTK and mechanisms of RICTOR in tumor growth, metastasis and drug resistance." (PMID 32041519, 2020). "Here, we discuss the biology of RICTOR in tumor and the prospects of targeting RICTOR as a complementary therapy to inhibit RTK co-activation." (PMID 32041519, 2020). "Subsequent in vitro and in vivo experiments suggested that RICTOR blockade impaired tumor growth via decreasing the activation of the AGC kinase and decreasing the expression of hypoxia-inducible factor 1-alpha (HIF-1α) and VEGF-A." (PMID 32041519, 2020). "Based on chi‐squared and Fisher’s exact tests, we found RICTOR expression positively related to tumor site (P = 0.0018)." (PMID 31393061, 2019). "Here, we have explored RICTOR/mTORC2 in HNSCC tumor cells and interrogated the role of mTORC2 in modulating response to PI3K inhibition." (PMID 31393061, 2019). "An indirect supporting evidence for RICTOR dependence is perhaps the correlation between RICTOR expression – tumor stage and tumor size found in our multivariate analysis of overall survival in PROSPECT (data not shown)." (PMID 30338041, 2018). "Using a PDAC genetically engineered mouse model (GEMM), it was also shown that RICTOR deletion dramatically delayed tumor formation, whilst mice with median survival almost doubled in RICTOR-deleted mice compared with control mice." (PMID 29455662, 2018). "Collectively, these findings suggest that AZD2014, in combination with selumetinib, results in significant anti-tumor activity of RICTOR/KRAS-altered LUAD, through simultaneous blockade of mTORC1/2 and MEK pathways." (PMID 30338041, 2018). "In CRC cells, RICTOR expression is also regulated by the miR-424/503 cluster, which contributes to tumor progression." (PMID 29455662, 2018). "In accordance with the in vitro data, these same authors found that the 86% of tumor samples had RICTOR overexpression and 70% of them showed high mTORC2 activity." (PMID 30662577, 2018). "Elevated RICTOR expression was also found in GC and directly correlated with tumor size, invasion of stomach wall, infiltration of lymph node and vessels, tumor stage and differentiation." (PMID 29455662, 2018). "Continuous induction of RICTOR knockdown for 6 weeks translated to a significant reduction of xenograft tumor growth compared to control groups (P < 0.05)." (PMID 30338041, 2018).
tumor (continued). "Taken together, these studies attest that RICTOR amplification and overexpression play a role in tumor growth, at least in part via vascularization and remodeling of the tumoral stroma." (PMID 29455662, 2018). "Stable knock-down of RICTOR led to significant inhibition of tumor volume which was also reflected by decreased final tumor weights." (PMID 28445935, 2017). "Assessment of RICTOR blockade in vivo demonstrated a significant inhibition of subcutaneous tumor growth and development of orthotopic PDAC xenografts." (PMID 28445935, 2017). "Stable RICTOR knock-down led to significant inhibition of tumor growth in subcutaneous and orthotopic tumor models which was accompanied by significant reduction of tumor cell proliferation." (PMID 28445935, 2017). "In this respect we found that expression of SGK1 (also an AGC kinase) is impaired upon RICTOR blockade, which is likely related to the impairment in IL-8 secretion from tumor cells." (PMID 28445935, 2017). "Similar to the effects in L3.6pl cells, RICTOR knock-down led to markedly decreased tumor volumes and weights." (PMID 28445935, 2017). "In line with our in vitro results, RICTOR blockade reduced tumor vascularization versus respective controls." (PMID 28445935, 2017). "In vivo, RICTOR inhibition led to marked inhibition of tumor growth at least in part via impairment of AKT phosphorylation." (PMID 28445935, 2017). "RICTOR, the mTOR component 2, was a direct target of miR-218 and miR218-RICTOR-VEGFA axis was the mechanism inhibiting the tumor angiogenesis of PCa cells." (PMID 28030804, 2017). "Results demonstrate that depletion of RICTOR with siRNA (transient knock-down) or shRNA (stable knock-down) has an inhibitory effect on tumor growth in vitro." (PMID 28445935, 2017). "First L3.6pl [L3.6pl (ctrl-sh), L3.6pl (RIC-sh1)] were used to address this issue, showing that RICTOR inhibition significantly impairs the final tumor volume as determined upon necropsy on day 25 after tumor cell injection." (PMID 28445935, 2017). "We further validated the enhanced RICTOR expression in luminal tumor tissues by immunofluorescence." (PMID 40934285, 2025). "After analyzing The Cancer Genome Atlas MM patients’ database to explore both overall survival and molecular signatures as a function of intra-tumor RICTOR levels, we investigated the effects of RICTOR downregulation in BRAFV600E MM cell lines on their response to BRAF/MEKi." (PMID 38755661, 2024). "Notably, combining 5-FU and BPTES resensitized RICTOR-null tumours, reducing their growth comparably to 5-FU monotherapy of controls." (PMID 39080411, 2024). "Mice bearing RICTOR-null tumours received 5-FU alone or with BPTES." (PMID 39080411, 2024). "RICTOR-null tumours grew significantly slower than controls." (PMID 39080411, 2024). "Moreover, the CRISPR Achilles’ knockout analysis revealed that RICTOR was a critical gene for the survival of many tumor cells." (PMID 37372460, 2023). "we could validate RICTOR amplification first by FISH in several main tumour types, where previously potentially targetable Rictor overexpression or increased NGS CNV had been highlighted; c." (PMID 37949943, 2023). "A similar frequency of RICTOR gene alterations was found in several tumour types." (PMID 37949943, 2023). "Taken together, these results suggest that RICTOR may promote tumor cell growth by regulating the cell cycle." (PMID 37372460, 2023). "Finally, we validated the ability of RICTOR in sustaining tumor growth and invasion in the Hela cell line using cell-cycle analysis, the cell proliferation assay, and wound-healing assay." (PMID 37372460, 2023). "RICTOR is a scaffold protein that activates mTORC2 complex constituting mammalian Target of Rapamycin or mTOR, an intracellular serine/threonine kinase involved in intracellular cell survival, tumor growth, and drug resistance." (PMID 32724061, 2020).
tumor (continued). "To evaluate how loss of negative feedback to RICTOR/mTORC2 affected Akt phosphorylation in HNSCC tumor cells, we examined Akt phosphorylation following PI3K inhibition by BYL719 (5 μm) for up to 72 h." (PMID 31393061, 2019). "RICTOR deregulation could have important effects in tumor development either because it cooperates with altered RTKs to transform cells or as a critical regulator of a major pathway downstream of RTKs." (PMID 29455662, 2018). "To determine whether the synergistic effects seen in vitro translated into anti-tumorigenic effects in vivo, we utilized inducible shRICTOR-H1792 cells (RICTOR amplified, mutKRAS) to establish tumor xenografts in mice." (PMID 30338041, 2018). "Effects on tumor metabolism could be linked to inhibition of AKT and HIF-1α phosphorylation/expression by RICTOR blockade that we observed; since both factors are key players in metabolic reprogramming." (PMID 28445935, 2017). "Moreover, in vivo tumor growth was significantly decreased in subcutaneous and orthotopic models upon RICTOR knock-down." (PMID 28445935, 2017). "In addition, immune microenvironment analysis and gene function analysis suggests potential mechanisms that RICTOR may regulate tumor immunity, and sustain tumor growth and proliferation." (PMID 37372460, 2023). "Because we were interested in the effect of mTORC2 signaling on the therapeutic efficacy of PI3K inhibition in HNSCC tumor cells, we made use of the cBioPortal interface to evaluate whether aberrations in these genes (RICTOR and PIK3CA) tend to co‐occur or be exclusive from one another." (PMID 31393061, 2019). "RICTOR silencing blocked tumor mTORC2 signaling and growth in multiple TNBC mouse models while also improving TNBC tumor response to chemotherapy." (PMID 40019775, 2025). "We now asked how RICTOR regulates the UGCG expression and how UGCG-mediated glucosylceramide synthesis enhances tumor progression." (PMID 40934285, 2025). "We utilized clinically relevant mTOR inhibitors capable of mTORC1-selective or dual mTORC1/2 blockade to elucidate the important role of mTORC2 signaling in tumor cell survival and dissected their effects in various TNBC cells harboring RICTOR amplification." (PMID 40019775, 2025). "We observed an abundant increase in RICTOR expression and high expression of pAKT and UGCG in tumor tissues." (PMID 40934285, 2025). "ITGA10 transmitted specific signals through TRIO and RICTOR, activating RAC/PAK and AKT/mTOR pathways to promote tumor cell survival." (PMID 40258773, 2025). "Reduced RICTOR expression resulted in elevated NAMPT expression and increased mitochondrial respiration, contributing to the intrinsic tolerance of drug-naïve tumor cells to BRAF/MEK inhibition and fostering a BRAF inhibitor-resistant phenotype." (PMID 40775221, 2025). "We further demonstrate that RICTOR regulates the synthesis of GD3 gangliosides through ZFX and UGCG, and triggers the activation of the EGFR signaling pathway, thereby promoting tumor growth." (PMID 40934285, 2025). "In conclusion, our study demonstrates that KLF4 functions as a tumor suppressor and inhibits the progression of HCC through the miR206/RICTOR axis." (PMID 39000273, 2024). "Using the HMGB1 and RICTOR-manipulated cell lines we found that downregulation of HMGB1 and RICTOR mRNAs significantly inhibited tumor spheroid growth and cell proliferation in vitro." (PMID 34916485, 2021). "Alterations in cell cycle regulatory genes were also detected in the tumor DNA of patients enrolled in the phase Ib BISCAY trial, in which 15% of patients with UC carried an amplification in RICTOR or a deleterious alteration in TSC1/TSC2." (PMID 34030643, 2021). "We further define novel roles for mTORC2/RICTOR and Sestrin3/GATOR2/WDR59 in promoting TNBC tumor growth." (PMID 34031411, 2021). "RICTOR, the core component of the PI3K/Akt pathway, has been shown to be involved in tumor survival and drug resistance." (PMID 32041519, 2020).